STAT3 (signal transducer and activator of transcription 3)
Diseases named in the same sentence as STAT3 in open-access papers (continued):
Sharing a sentence is not in itself a finding about the gene and the disease.
tumor (continued). "In the tumor microenvironment, IL-6/JAK/STAT3 signaling induced the expression of factors that promotes angiogenesis such as VEGF and invasiveness such as matrix metalloproteinases, while strongly suppressing the antitumor immune response." (PMID 33917399, 2021). "STAT3: Among the seven members of the STAT protein family (STAT1, STAT2, STAT3, STAT4, STAT5a, STAT5b, and STAT6), STAT3 and STAT5 are the most important factors for tumor progression." (PMID 34079469, 2021). "Using this platform, we developed potentially novel PS-conjugated STAT3, MYC, and Gp130 peptides that effectively and specifically block activated STAT3 axis and MYC function in tumor cells and in tumor microenvironment." (PMID 33491667, 2021). "STAT3 and ERK are activated by common interleukins in a tumor microenvironment like IL-10, TNF-α, and IL1β." (PMID 34177892, 2021). "Our findings demonstrate that inhibition of p-STAT3 signaling by Stattic decreased IL10-promoted tumor growth and tumor volume." (PMID 33500726, 2021). "IL-6, through its ability to signal via the STAT3-JAK pathway, can enhance tumor cell survival, promote osteoblast and tumor cell production of RANKL and PTHrP to induce osteoclastogenesis, induce angiogenesis, and modulate immune cell function." (PMID 33805598, 2021). "In the present study, we investigated the effects of Anwulignan treatment on the growth of NSCLC cells and tumours and its role in modulating the JAK1/STAT3 signalling pathway." (PMID 33523587, 2021). "STAT3 has been reported to regulate the expression of membrane metalloproteases (MMPs), TWIST1 and VEGF which are responsible for tumor invasion, migration and angiogenesis." (PMID 33794890, 2021). "Notably, STAT3 is an emergent target anti-cancer therapy, and data have indicated that STAT3 inhibition in immune cells may reprogram these cells to a tumoricidal phenotype, reduce tumor cell proliferation, angiogenesis, and metastasis." (PMID 33435371, 2021). "Meanwhile, STAT3 cascade blocking has been shown to significantly decrease the IDO expression in MDSCs, tumor development, and metastasis." (PMID 33957948, 2021). "Conversely, PARK2 overexpression was shown to inhibit tumour growth and angiogenesis via the JAK2/STAT3/VEGF pathway in vivo and in vitro." (PMID 33382511, 2021). "On the other side, the activation of M2 macrophage polarization is mediated by a predominance of STAT3 and STAT6, resulting in immune suppression and tumor progression." (PMID 33522932, 2021). "This is in contrast to the tumor suppression by cancer cell–intrinsic PDLIM2, which depends on both STAT3 and RelA." (PMID 33539325, 2021). "As reported, JAK/STAT1, JAK/STAT3, and JAK/STAT5 are three classic pathways that play a crucial role in tumor progression." (PMID 35047409, 2021). "Pre-clinical studies have revealed an unequivocal role for tumor cell-intrinsic and extrinsic STAT3 signaling in NSCLC by promoting angiogenesis, cell survival, cancer cell stemness, drug resistance, and evasion of anti-tumor immunity." (PMID 34944848, 2021). "Inhibition of lipid uptake by genetic depletion of the FA translocase CD36, or inhibition of the STAT3 or STAT5 signal, results in an impaired immunosuppressive function in MDSCs and delayed tumor growth." (PMID 34766135, 2021). "Regarding this, interleukin (IL)-6, signaling through the signal transducer and activator of transcription 3 (STAT3), has shown to promote tube formation by tumor cells in vivo and in vitro by upregulating VE-Cadherin expression and MMP2 activity." (PMID 34359928, 2021). "The tumor tissue proteins were extracted, and Western blot was used to analyze the expression of MARCH1 and molecules in the p38 MAPK/Stat3 signaling pathway." (PMID 34733155, 2021).
tumor (continued). "Taken together, consistent with in vitro studies, our results suggested that apatinib inhibited the tumor growth of NSCLC cells by targeting both Nrf2 and VEGFR2/STAT3 signaling in vivo." (PMID 34429133, 2021). "IHC validation on tumor samples showed an activation of the FGFR2 downstream targets AKT, p44/p42 MAPK, p38 MAPK, STAT1, and STAT3." (PMID 34480077, 2021). "Our work also validated that cinobufagin inhibited tumor growth and elongated nude mice life span via blocking EGFR and STAT3 signaling pathways and inducing apoptosis in vivo." (PMID 34925034, 2021). "This study defined a tumor-selective cytotoxic “bystander” role for secreted MDA-7 protein and identified a novel receptor-mediated, STAT3-independent, and PKR-independent death pathway." (PMID 35008495, 2021). "Through activation of the STAT3/SNAIL pathway, cisplatin treatment rendered drug resistance, enhanced the EMT-like phenotype, and increased migration and invasion abilities in tumour cells." (PMID 33806019, 2021). "Stat3-blocked lysates of whole HCC cells stimulated activation of T and natural killer (NK) cells and enhanced cytotoxic CD8 T cell infiltration in tumor tissues." (PMID 34869376, 2021). "Like STAT3, COX2 is a pleiotropic factor involved in tumor initiation, progression, and inflammatory signaling and COX-2 inhibitors decrease the incidence of gastrointestinal tumors in mice and humans as well as a subset of tumors arising in other tissues." (PMID 34572547, 2021). "Disruption of tumor-derived NLRP3, either pharmacologically or genetically, reduced STAT3 signaling in bone marrow cells." (PMID 34531850, 2021). "STAT3 is a key transcriptional regulator of MDSC function and expansion and is significantly upregulated in MDSCs of tumor-bearing mice compared to immature myeloid cells in naïve mice." (PMID 34944848, 2021). "Western blot analysis of whole tumor extracts demonstrated decreased expression of the human-specific GSC markers SOX2 and OLIG2 and reduced levels of p-STAT3 compared with the controls." (PMID 33986188, 2021). "Fluspirilene inhibited STAT3, resulting in decreased GBM proliferation, invasion and tumor growth, penfluridol decreased colony sphere number and size with reductions in (sex determining region Y)-box 2 (SOX2) and octamer-binding transcription factor 4 (OCT4)." (PMID 33919596, 2021). "In HCC, the lncRNA DLX6-AS1 is involved in the STAT3 signaling pathway, which regulates the expression of CADM1 and participates in tumor progression." (PMID 34395444, 2021). "These exosomes activate the AKT, STAT3, and ERK pathways in recipient cells, thereby decreasing the sensitivity of tumor cells to ceritinib and ultimately promoting tumor growth." (PMID 33628582, 2021). "For instance, cancer-associated fibroblast (CAF)-derived IL-6 interacts with the IL-6 receptor to activate STAT3 and ERK1/2 signaling pathways that promote tumor growth in gastrointestinal cancer." (PMID 33406733, 2021). "It showed that the tumor size and tumor weight was obviously decreased after EZH2 knockdown while the decreased tumor size and tumor weight was recovered by WT STAT3 overexpression." (PMID 34335938, 2021). "In a previous study, we found that STAT3, an important driver for CRC tumorigenesis and metastasis, was overexpressed in human CRC tissues compared with adjacent non-tumor colorectal tissues." (PMID 34526411, 2021). "Expression of phospho-STAT3 and MECA32 staining was also examined from primary tumor tissues to examine the effect of MAFF and IL11 on STAT3 pathways and microvessel density." (PMID 34262028, 2021). "Icaritin reduced the expression of Arg-1 in tumor-infiltrating PMN-MDSCs from the tumors of orthotopic Hepa mice, and inhibited STAT3 activation in PMN-MDSCs." (PMID 33717093, 2021). "The generation of ROS levels in cancer cells prompted by 27-hydroxycholesterol (27HC) and deferoxamine (DFO) activates STAT-3/VEGF and ERK1/2/HIF1α signaling pathways, promoting tumor angiogenesis and metastasis." (PMID 33916438, 2021).
tumor (continued). "In this process, leptin, a secreted adipokine from adipocytes, has been reported to stimulate STAT3 and CPT1B by binding to the leptin receptor or PD-1 on CD8+ T cells, suppressing their glycolysis and anti-tumor ability." (PMID 34742349, 2021). "Comparable to STAT3, STAT5B is also expressed by a large fraction of the tumour cells, and a high proportion of the protein is located in the nucleus." (PMID 34680385, 2021). "STAT3 seemed to reduce the antitumor activity of CD8+ T cells and to expand the tumor-promoting Th17 lymphocytes, and it was also important for generating memory T-cells and long-term antitumor immunity." (PMID 34830179, 2021). "The interactions of PDAC tumor cells and different cells within the TME such as CAFs, MDSCs, TAMs, are mediated through GP130/JAK/STAT3 pathway." (PMID 34138876, 2021). "Next to STAT3, STAT5 has been highly investigated in PCa, and its role in tumor progression has been described." (PMID 34638338, 2021). "Both Resveratrol (RSV) and Dendrosomal Curcumin (DNC) are revealed to downregulate the expression levels of IL-10 and Arg1 on TAM through the inactivation of STAT3 to reduce the numbers of TAM, further inhibiting tumor growth and metastasis." (PMID 33748122, 2021). "Consistent with the cellular data, Alp treatment also restored the decreased PPAR-γ expression levels and inhibited STAT3 and NF-κB phosphorylation in gastrocnemius muscles of LLC tumor–bearing mice as shown by the Western blot." (PMID 34093209, 2021). "Intriguingly, in a powerful genetically engineered mouse model that develops MPNST, activated STAT3 emerges at the ANNUBP stage and then is significantly higher when these tumours undergo malignant transformation." (PMID 33658640, 2021). "Curcumin can inhibit several tumor-specific pathways, such as NF-κB, STAT3, PI3K/AKT, and Sonic Hedgehog, allowing it to selectively destroy tumor cells while sparing healthy tissues." (PMID 34204169, 2021). "We found that RIPK4 promotes tumour progression by promoting the invasion and metastasis of HCC and illustrated the close relationship between RIPK4 and the STAT3 pathway." (PMID 34222329, 2021). "IHC staining revealed that αPD-L1 Ab in combination with NPs-Stattic-IL20RA inhibited the expression of p-STAT3 (Tyr705) and SOX2 in tumor tissues compared with IgG, αPD-L1 Ab, NPs-Stattic, and NP-Stattic-IL20RA plus IgG treatment, respectively." (PMID 33456560, 2021). "As discussed in the previous section, deleting STAT3 in the MTB/tetO-MIC model results in immune-system remodeling and complete elimination of hyperplastic growth, dramatically delaying tumor onset." (PMID 33235291, 2021). "Elevated expression of phosphorylated STAT3 and NF-kB/TIM4 was observed in tumor cells after IL-6 stimulation." (PMID 34657635, 2021). "A statistical analysis of all 42 tumour samples, including EATL I, EATL II and PTCL-NOS, revealed the activation of STAT3 in 82.35% of all tumour cells examined, as determined by the ratio between cytoplasmic and nuclear localisation." (PMID 34680385, 2021). "When compared with the differentiated cells of triple-negative breast cancer cells, the stemness-bearing CD44+CD24− cell population has a preferentially higher activity in the IL-6/JAK/STAT3 pathway, leading to CSC proliferation and tumor growth." (PMID 34202411, 2021). "Further, the co-activation of STAT3 and NF-κB was involved in the PAR1 activation-induced tumor promoting effect, while only NF-κB participated in the PAR4 activation-induced tumor inhibitory effect in ESCC." (PMID 34844621, 2021). "STAT3 functions in inflammation, angiogenesis, and tumor progression, and both HMGA1 and STAT3 are up-regulated and co-expressed in hematologic malignancy." (PMID 34572547, 2021). "The structural activation of STAT3 is a common feature of NSCLC, and it is also considered to play an important role in tumor resistance to conventional and targeted small molecule therapy, especially the rich mutations in the JAK/STAT pathway." (PMID 34079469, 2021).
tumor (continued). "Overexpression of PARK2 inhibited tumor growth, invasion, and angiogenesis, probably through suppressing the JAK2/STAT3/VEGF signaling pathway in OS." (PMID 34691358, 2021). "It was found that the number of metastatic nodules in murine liver tissues was significantly reduced after STAT3 knockdown or PTEN overexpression, whereas miR-19a mimic increased the tumor metastasis in vivo." (PMID 34796092, 2021). "STAT3 is constitutively activated and highly acetylated in the HCC and contributes to tumor progression by inducing the methylation of tumor suppressor genes." (PMID 34440160, 2021). "This phenomenon was accompanied by the increase of specific marker expression and cytokine release in CAFs, as well as the increase of tumor sphere formation and up-regulation of MEK1/2, ERK1/2, STAT3 plus β-catenin in NSCLC cells." (PMID 34885115, 2021). "The tumour‐promoting functions of the JAK2/STAT3 signalling pathway have been well recognized in various malignancies, and JAK2/STAT3 participates in promoting EMT and enhancing the stemness of OSCC." (PMID 33289330, 2021). "Knock-out of Stat3 in T cells or using an FAO inhibitor enhances glycolysis and anti-tumor functions, eliminating breast tumors." (PMID 34742349, 2021). "Constitutive STAT3 and mitogen‐activated protein kinase (MAPK) signalling is involved with tumour immune evasion of human melanomas." (PMID 33382511, 2021). "In this work, we adapted mathematical modelling to investigate the role of regulatory cytokines (IFN-β, JAK2) on tumour growth through the corresponding intracellular signalling networks and mutual inhibition mechanism between STAT1 and STAT3." (PMID 34631119, 2021). "The combination of STAT3 and VEGF inhibition with AZD1480 and cediranib, respectively, led to significantly decreased angiogenesis and tumor volume in a murine model." (PMID 33498872, 2021). "The IGF-1R siRNA/DOX co-delivery system loaded chitosan nanoparticles play an effective role in reducing mmp9, STAT3, and VEGF in tumor cells." (PMID 33768092, 2021). "JAK2/STAT3/VEGF signalling is activated during angiogenesis in vivo, and tumour suppressor gene, PARK2, was shown to inhibit tumour growth and angiogenesis in vivo by downregulating the JAK2/STAT3/VEGF pathway." (PMID 33382511, 2021). "STAT3 is a key regulator of MDSC biology, as its genetic ablation in tumour-bearing mice abrogates MDSC expansion." (PMID 34685679, 2021). "STAT3-regulated exosomal miR-21, for example, enhances vascular endothelial growth factor (VEGF) expression, and thus stimulates tumor angiogenesis and induces malignant bronchial epithelial cell transformation." (PMID 34572829, 2021). "Anlotinib targets JAK2/STAT3/VEGFR signaling, and the inhibition of angiogenesis halts tumor proliferation and promotes apoptosis." (PMID 34955687, 2021). "In cell-based assays and in various xenograft tumor models, AZD1480 demonstrated inhibition of Stat3 and Stat5." (PMID 34680353, 2021). "A previous study applied chromatin immunoprecipitation assays to reveal that the STAT3 protein binds to the VEGFA promoter in vivo and found that constitutive STAT3 activity upregulates VEGFA expression and increases tumor angiogenesis." (PMID 34059068, 2021). "Compared to uncommitted macrophages, tumor-polarized myeloid TAMs and MDSCs were characterized by the predicted activities of c-MYC, SPI and STAT3." (PMID 34208043, 2021). "After blocking the IL-6/STAT3 pathway, HCC cells co-cultured with macrophages exhibit cell apoptosis, reduced drug resistance, suppressed cell invasion, migration, and tumor formation; all are indicators of the enhanced tumor suppressive function of M1." (PMID 34696292, 2021). "Consistently, the tumour tissues exhibited higher levels of CREPT and p-STAT3 than adjacent normal tissues both in breast and colon cancer." (PMID 33531691, 2021).
tumor (continued). "Diverse signaling cascades that are atypically activated or inactivated during tumor progression, such as JAK/Stat3, PI3K/Akt, TGF-β/Smad, as well as Wnt/β-catenin, have been found responsible for regulating the EMT process." (PMID 33762939, 2021). "In this study, we identified an ERK/STAT3-dependent mechanism whereby TRAIL induces PD-L1 expression, which in turn promotes EMT and tumor progression in ESCC." (PMID 34167551, 2021). "Although well reported for its functions in tumour proliferation, survival, invasion and immunosuppression, JAK1/STAT3 signalling also contributes to drug resistance in NSCLC." (PMID 33523587, 2021). "While W2014-S exhibited more potent anti-tumor activities in primary studies and selectively inhibited aberrant STAT3 signaling in NSCLC, demonstrating significant anti-tumor activities in cell and animal models." (PMID 33391507, 2021). "It was revealed that in GC tumor tissues and GC cells, in contrast with the Vector group, CALM2 overexpression greatly facilitated JAK2 and STAT3 phosphorylation and elevated the protein expressions of HIF-1 and VEGFA." (PMID 34604066, 2021). "Studies utilizing AML xenograft models in vivo confirmed the in vitro findings, wherein Zotiraciclib induced effective blockade of Stat3, Stat5 and CDK signaling leading to tumor regression and prolonged survival of mice carrying the tumors." (PMID 34680353, 2021). "Meanwhile, treatment of tumor-bearing mice with the STAT3 inhibitor LL1 sensitizes resistant A549 NSCLC tumors to gefitinib and leads to a synergistic anti-tumor response." (PMID 34944848, 2021). "Recent studies suggest that the signal transducer and activator of transcription 3 (STAT3) is a key transcription factor that regulates the function of CAFs, and their crosstalk with tumor and immune cells within the TME." (PMID 34858425, 2021). "Overall, we conclude that STAT3 and STAT5B are expressed in practically all tumour cells of the feline EATL I, EATL II and PTCL-NOS samples examined and show a high level of activation in these cells." (PMID 34680385, 2021). "Although both IL-6 and HGF activate STAT3 and induce ZEB2, they seem to play a different role in tumor progression." (PMID 34408135, 2021). "During tumor progression, specific endogenous ligands activate downstream pathways including the Ras/Raf mitogen-activated protein kinase (MAPK), Jak2/Stat3, and PI3K/AKT pathway." (PMID 32685551, 2020). "This revealed that si-STAT3 and R848 treatment of MDSCs significantly reduces the proliferation of MCF-7 tumor cells." (PMID 33679700, 2020). "In a breast cancer model, lactate was shown to activate the ERK/STAT3 signaling pathway and thereby TAM polarization and M2 macrophage differentiation, which in turn promoted tumor proliferation, migration and angiogenesis." (PMID 33153193, 2020). "In summary, our data show that PP VII resulted in alteration of gene expression programs in macrophage transformation to enhance anti-tumor immunity and restrain immunosuppression via STING-dependent type I IFN and STAT3 signaling." (PMID 33288772, 2020). "Previous research by the research group found the elevated STAT3 and EGFR in the tumor tissues from HNSCC patients." (PMID 32577124, 2020). "Therefore, the STAT3 signaling pathway may contribute to the modulation of metabolism through diverse PTMs to provide a metabolic advantage to cancer cells, thereby promoting tumor cell proliferation and tumorigenesis." (PMID 33003453, 2020). "Inhibition of STAT3 recovered the CXCL9-inhibited proliferation, activation, and secretion of anti-tumour cytokines of CD8+ T cells." (PMID 31913856, 2020). "Activation of STAT3 contributes to hypoxia-inducible factor 1 alpha (HIF-1α) and vascular endothelial growth factor (VEGF) expression in tumor cells, while VEGF in turn activates STAT3 in endothelial cells." (PMID 32664527, 2020).